EPCAM (epithelial cell adhesion molecule)
Diseases named in the same sentence as EPCAM in open-access papers (continued):
Sharing a sentence is not in itself a finding about the gene and the disease.
neuroblastoma (7 papers, 2009 to 2022). Neuroblastoma (NB) is the most common solid, extracranial childhood tumor. "To use the CellSearch CXC kit for investigating CCT2 in the detection of neuroblastoma cells shed in blood, we first confirmed that the IMR-32 cells express EpCAM." (PMID 36185250, 2022). "Here, we focus on the pediatric cancer neuroblastoma, a malignancy of neuro-endocrine origin, which does not express the epithelial marker EpCAM." (PMID 25133137, 2014). "DTCs from neuroblastoma patient samples were isolated based on expression of the cell surface marker GD2, while spiked cell line tumor cells were detected and captured by labeling for GD2, HER2 (breast), EGFR (NSCLC), and EpCAM (colon)." (PMID 25133137, 2014).
prostate adenocarcinoma (7 papers, 2013 to 2025). "Our results indicate that PIM-1 is overexpressed at a high frequency in EpCAM(+) CTC fraction in mCRPC (37.5%), when compared to the TCGA data in prostate adenocarcinoma primary tumors (6%)." (PMID 32397108, 2020). "Epithelial cell adhesion molecule (EpCAM) and cathepsin L (CTSL) are epithelial proteins that have been found abundantly expressed in prostate adenocarcinomas." (PMID 24289299, 2013).
renal cell carcinoma (7 papers, 2010 to 2024). "The epithelial cell adhesion molecule (EpCAM) is a ~ 40kDa transmembrane glycoprotein located on chromosome 2p21, highly expressed in most epithelial cancers except squamous, urothelial and renal cell carcinomas." (PMID 35070966, 2021). "It is also known today that noninvasive imaging of EpCAM expression has produced good results using nuclear medicine techniques in the case of renal cell carcinoma (RCC) in animals." (PMID 39199590, 2024). "Most conventional approaches for capturing CTCs use an EpCAM-based enrichment strategy, which does not work well in cancers that show low or no expression of EpCAM, such as renal cell carcinoma (RCC)." (PMID 27494883, 2016). "Other less prevalent malignant kidney tumors included a renal cell carcinoma (RC), which showed a CD271+ CD81+ EpCAM+ CD71+ CD117+ phenotype in the absence of CD9, CD10, CD58, CD90, CD105, and GD2, and a clear cell sarcoma, which expressed CD271+ and GD2+ without EpCAM." (PMID 34638431, 2021).
anaplastic thyroid cancer (6 papers, 2014 to 2026). "The data implies the association of EpCAM and CD44v6 in the clinical anaplastic thyroid cancers." (PMID 24727741, 2014). "Okada et al17 found that the expression of EpCAM in two anaplastic thyroid cancer cell lines (FRO and ACT‐1) were remarkably higher than those in the TPC‐1 and FTC‐133 cells." (PMID 30039914, 2018). "In contrast, nuclear expression of EpCAM was detected in 24 of 37 (64.9%) anaplastic thyroid cancers." (PMID 24727741, 2014). "On the other hand, loss of membranous expression and increased nuclear accumulation of EpCAM is observed in the anaplastic thyroid carcinomas in the immunohistochemical analysis of clinical specimens." (PMID 24727741, 2014). "With regard to claudin-7, its expression was significantly higher in the anaplastic thyroid cancer cell lines, which showed a higher EpCAM expression as well." (PMID 24727741, 2014). "In the present study, we demonstrated that EpCAM, together with CD44 and claudin-7, is associated with the phenotype of anaplastic thyroid cancer both in the established cell lines and clinical specimens." (PMID 24727741, 2014). "This study aimed to examine how EpCAM and its related molecules are involved in the characteristics of anaplastic thyroid carcinoma." (PMID 24727741, 2014). "Thus, EpCAM and CD44s were inversely expressed in these four cell lines, with the anaplastic thyroid cancer cell lines expressing higher levels of EpCAM and lower levels of CD44s compared with the differentiated cancer cell lines." (PMID 24727741, 2014). "Interestingly, double immunofluorescence staining assay demonstrated that ALDH1 was expressed mostly in the EpCAM positive cells in the anaplastic thyroid cancer cell lines." (PMID 24727741, 2014). "However, to the best of our knowledge, the association of EpCAM, CD44v6 and claudin-7 have not been evaluated in anaplastic thyroid carcinoma." (PMID 24727741, 2014). "Comparison of localization of EpCAM and CD44 expression in clinical anaplastic thyroid cancers (N = 37)." (PMID 24727741, 2014). "The expression of CD44s was detected in 36 of 37 anaplastic thyroid cancers regardless of the localization of EpCAM." (PMID 24727741, 2014). "Our study suggests the possibility that EpCAM, together with CD44v6 and claudin-7 as well as ALDH1, may be involved in the development of the aggressive phenotype of anaplastic thyroid carcinoma." (PMID 24727741, 2014). "In conclusion, our study suggests the possibility that EpCAM, together with CD44v6 and claudin-7 as well as ALDH1, may be involved in the development of the aggressive phenotype of anaplastic thyroid carcinoma." (PMID 24727741, 2014). "Although direct interaction of EpCAM, CD44 variants, and claudin-7 was not examined in our study, the results suggest that complexes of EpCAM with CD44 variants and claudin-7 may be associated with the aggressive phenotype of anaplastic thyroid cancer." (PMID 24727741, 2014).
Enteropathy (6 papers, 2019 to 2023). "Our findings provide new insights into the role of EpCAM and the etiology of the enteropathies driven by Spint2 deficiency." (PMID 37539662, 2023). "Despite its widespread expression, loss of EPCAM function has so far only been reported to prominently affect intestinal development, resulting in severe early onset enteropathy associated with impaired growth and decreased survival in both humans and mice." (PMID 35730316, 2022).
epithelioid mesothelioma (6 papers, 2014 to 2025). "In epithelioid mesotheliomas, 9.1% were positive for EpCAM alone, 13.6% were positive for TROP2 alone, and only 4.5% for both EpCAM and TROP2." (PMID 38786342, 2024).
esophageal adenocarcinoma (6 papers, 2015 to 2026). A malignant tumor with glandular differentiation arising predominantly from Barrett mucosa in the lower third of the esophagus. "Epithelial cell adhesion molecule (EpCAM), a pro-oncogenic glycoprotein, has been identified as an upregulated protein in esophageal adenocarcinoma (ESCA) through multi-OMICS platforms." (PMID 41769390, 2026). "Among the epithelial markers measured, BE samples are characterized by a higher percentage of epithelial cells (CD45-, EpCAM+) including cells expressing Her2, a marker of BE and esophageal adenocarcinoma, and the cell adhesion marker CD49f." (PMID 31217895, 2019). "The expression of EPCAM was examined in detail by IHC in an independent cohort of 115 esophageal adenocarcinomas with matched normal and metastatic tissues." (PMID 28336725, 2017). "SK‐GT‐4 oesophageal adenocarcinoma cells were incubated with fluorescently‐conjugated antibodies against EpCAM, cytokeratins 4, 5, 6, 8, 10, 13 and 18, and with DAPI, a fluorescent dye that binds DNA." (PMID 26178530, 2016). "Here, the expression of EpCAM was determined by Western blotting in three cell lines, HET 1-A representing benign esophageal epithelium, Bar-T representing pre-malignant Barrett’s metaplasia and OE-19 representing esophageal adenocarcinoma, respectively." (PMID 30116994, 2018).
gastric adenocarcinoma (6 papers, 2005 to 2023). "Our data demonstrate the presence of a subset of cells with a CD24+CD44+CD54+EpCAM+ phenotype in gastric adenocarcinomas from 127 patients." (PMID 36737794, 2023).
invasive breast carcinoma (6 papers, 2003 to 2021). A carcinoma that infiltrates the breast parenchyma. "Another recent study indicated that the so-called normal genotype of invasive breast cancer, which accounts for approximately 10% of all cases, is typically negative for EpCAM expression and may thus be a cause of false-negative CTC determinations." (PMID 22646670, 2012).
kidney cancer (6 papers, 2020 to 2024). Primary or metastatic malignant neoplasm involving the kidney. "However, compared to other genitourinary tumors, less is known regarding CTCs in kidney cancer, mainly due to the low expression of EpCAM, the epithelial cell surface protein commonly used for CTC assays." (PMID 32098246, 2020). "Tumor cells from all 17 malignant kidney neoplasms studied showed expression of CD271+ and CD81hi, together with positivity for EpCAM in the majority (12/17) of tumors (70%) and CD90 in 5/17 (29%), while they systematically lacked CD57, CD58, CD99, CD117, nuMyoD1, and numyogenin expression." (PMID 34638431, 2021). "In turn, in the 15 WT (out of 17 malignant kidney tumors analyzed) samples, neoplastic cells co-expressed CD9, CD81, and CD271 in the absence of HLADR and GD2, usually in the context of an EpCAM+ (13/15, 86%) phenotype." (PMID 34638431, 2021).
steatosis (6 papers, 2014 to 2020). Increased lipid within the cytoplasm of cells. "Moreover, in NASH biopsies, PNPLA3 variant carriers showed higher degree of steatosis (p = 0.025), portal inflammation (p = 0.034), DR (p = 0.036), EpCAM+ hepatocytes (p = 0.029), and higher number of αSMA+ portal/septal MFs (p = 0.011) when compared with WT patients." (PMID 29150621, 2017). "We studied the tumorigenesis fate of EpCAM+ Hepa1-6 cells in 3 different liver microenvironments (normal, bland steatosis, and steatohepatitis) using an immunocompetent C57L/J mouse model." (PMID 32547703, 2020). "Control and HFD group of animals failed to initiate tumor, suggesting that healthy liver and bland-steatosis liver did not render an appropriate microenvironment for EpCAM+ CSCs survival." (PMID 32547703, 2020). "As regard clinical parameters, DR extension and the number of EpCAM-positive HPCs were correlated with ALT (r = 0.467; p<0.05 and r = 0.657; p<0.01, respectively) and with the steatosis grade assessed by liver ultrasonography (r = 0.490; p<0.05 and r = 0.632; p<0.01, respectively)." (PMID 24505350, 2014). "We demonstrate that the NASH liver is favorable to EpCAM+ CSC-mediated tumorigenesis in immunocompetent microenvironments, but not the normal liver or the nonprogressive bland steatosis." (PMID 32547703, 2020).
trichoblastoma (6 papers, 2011 to 2026). A benign hair follicle neoplasm with trichoblastic differentiation. "Morpheaform BCC express usually epithelial cell adhesion molecule (EPCAM) (BerEP4), cytokeratin 6 (CK6, that is negative in tricoepithelioma), Ki-67 (negative in trichoepithelioma), and androgen receptor (AR)." (PMID 29261131, 2017).
asthma (5 papers, 2017 to 2025). "We further confirmed the role of RhoA in TGFβ expression and signaling activation in the airway epithelium of an asthma mouse model by co-immunostaining with epithelial marker EpCAM." (PMID 33936062, 2021). "In addition, we detected TGFβ1 in the airway epithelial cells of an asthma mouse model by co-immunofluorescent staining TGFβ1 with epithelial cell marker EpCAM." (PMID 33936062, 2021). "Combining all these genes with the same directions of changes in EpCAM+ cells, AT2 cells, AP, BAS, and ciliated cells, there was significant enrichment for NRF2-mediated Oxidative Stress Response, HMGB1 Signaling and Airway Inflammation in Asthma." (PMID 35627266, 2022).
brain tumor (5 papers, 2020 to 2024). "Strong EpCAM expression was observed in LL/2 brain tumors until the end of the experiment, making it unlikely that antigen loss serves as a mechanism of therapy resistance." (PMID 39358663, 2024).
hereditary cancer (5 papers, 2015 to 2023). Malignant neoplasms occurring in families at a rate greater than that expected by chance and caused by germline mutations in a specific gene.
inflammatory bowel disease (5 papers, 2019 to 2024). A spectrum of small and large bowel inflammatory diseases of unknown etiology. "In benign inflammatory conditions, P504S negative CPCs have been detected, as well as EpCAM positive cells in patients with inflammatory bowel disease." (PMID 31759363, 2019). "However, knockdown of EpCAM in the colon of mice also could increase the severity of dextran sulfate sodium salt (DSS)-induced murine inflammatory bowel disease (IBD)." (PMID 35493520, 2022). "In addition, EpCAM reduction exacerbates the progression of inflammatory bowel disease (IBD), but its elevation is detrimental in cholestatic liver injury." (PMID 38791091, 2024).
invasive carcinoma (5 papers, 2015 to 2020). A carcinoma that is not confined to the epithelium, and has spread to the surrounding stroma. "EpCAM (also known as epithelial cell adhesion molecule), another surface transmembrane glycoprotein known to be expressed in some invasive carcinomas is involved in cell proliferation and metastasis and has been shown to protect CLDN-1 from degradation." (PMID 31952355, 2020). "In analyzing potential links between STIC and EIC cells and their respective invasive carcinomas, two of the identified proteins were of particular interest based on their involvement in gynecological cancer development: Epithelial cell adhesion molecule (EPCAM) and Calcyphosin (CAPS)." (PMID 33384952, 2020). "EpCAM: Epithelial cell adhesion molecule (EpCAM), also known as CD326, is a transmembrane surface glycoprotein found expressed in epithelia and some invasive carcinomas." (PMID 26633531, 2015).
lung fibrosis (5 papers, 2014 to 2025). "CDH1 or E cadherin is an epithelial cell adhesion molecule that regulates cell differentiation and morphogenesis, and is associated with lung fibrosis and cancer." (PMID 25306249, 2014). "To this end, we analyzed the proliferation dynamics of lineage-negative (CD45–, CD31–, EPCAM–, MCAM–) lung fibroblasts in 2 in vivo models of lung fibrosis." (PMID 40875468, 2025).
lung squamous cell carcinoma (5 papers, 2013 to 2024). "In most studies, technologies used to capture CTCs are based on their recognition by immunomagnetic beads coated with antibodies to Epithelial Cell Adhesion Molecule (EpCAM) and report from 6% to 20% of squamous cell lung cancer (SQCLC) patients with detectable CTCs." (PMID 26571236, 2015). "The immunohistochemistry experiments on lung squamous cell carcinoma show that the lung tissues SOX2, KRT 5, KRT14, EPCAM and PD-L1 have a significant expression." (PMID 36056339, 2022). "Therefore, we selected SOX2, KRT5 and KRT14 stemness gene proteins, PD-L1 immune related proteins, vimentin protein, and EpCAM protein, all of which influence epithelial carcinogenesis, to explore whether the mechanism at the cell level corresponds to lung squamous cell carcinoma pathogenesis." (PMID 36056339, 2022). "We isolated human CSCs (CD133+/EpCAM+) and non-CSCs (CD133−/EpCAM+) from a squamous cell lung cancer xenograft using fluorescence-activated cell sorting (FACS) and respectively collected a total of 9.19×104 (3.4%) and 2.18×106 (96.6%) live cells corresponding to the two subpopulations." (PMID 23527012, 2013).
mesenchymal tumor (5 papers, 2010 to 2022). "Again, we observed that low EpCAM expression was associated with high vimentin expression, suggesting that capture of mesenchymal tumors may be challenging with EpCAM based-methods and that other capture antibodies may be required to capture the full range of CTCs." (PMID 20838621, 2010). "The filtration platforms are not dependent on EpCAM expression and can capture circulating epithelial–mesenchymal tumor (EMT) cells." (PMID 33096708, 2020).
metastatic colorectal cancer (5 papers, 2020 to 2022). "Next, the number of EpCAM + EGFR + cells in blood samples of patients with metastatic colorectal cancer was determined." (PMID 35035479, 2022). "For instance, CTC detection in patients with metastatic colorectal cancer is improved when the CellSearch® system is combined with the AdnaTest® (AdnaGen GmbH, Langenhagen), which uses RT-PCR to detect EPCAM, EGFR, and CEA expression in the EpCAM-enriched cell fraction." (PMID 32764280, 2020). "Expression of EVs cancer markers, such as MUC1-CD277, a transmembrane protein involved in metastasis, A33 a glycoprotein found on most primary and metastatic colorectal cancers, and epithelial cell adhesion molecule (EPCAM), a transmembrane glycoprotein involved in tumorigenesis, were explored." (PMID 33108394, 2020). "We have shown that LuM1, a metastatic colorectal cancer (mCRC) cell line, expresses an array of CSC/CIC markers, including phosphorylated STAT3 signaling, activated β-catenin signaling, and EpCAM/CD326." (PMID 33562088, 2021).
pancreatitis (5 papers, 2020 to 2025). Inflammation of the pancreas. "For pancreatitis samples, 87% (+/−SEM 2.4%) were EpCAM-/FAP+; gating further results in 86% IL1R+ (+/−SEM 4.4%) and Ly6C+ (+/−SEM 4.3%) cells." (PMID 40523922, 2025). "Since epithelial cell adhesion molecule (EpCAM) is overexpressed in various tumors as well as tissues such as the pancreas, CAR-T therapy targeting EpCAM theoretically may induce pancreatitis, requiring particular vigilance." (PMID 40066440, 2025). "We used FACS to isolate 100 Cd45-neg; EpCAM+; Siglec f+ tuft cells and an equivalent number of Cd45-neg; EpCAM+; Siglec f-neg non-tuft epithelial cells from five mice with pancreatitis." (PMID 32116793, 2020).
urothelial carcinoma (5 papers, 2010 to 2024). A malignant neoplasm derived from the transitional epithelium of the urinary tract (urinary bladder, ureter, urethra, or renal pelvis). "EpCAM expression was found in 44-93% muscle-invasive urothelial carcinomas (average 61% EpCAM positive)." (PMID 38282671, 2023). "Previously we showed that EpCAM has a high tumor distinctiveness for LN metastases with urothelial carcinoma." (PMID 36581931, 2022). "Previously, EpCAM expression was highly found in lymph node metastases of prostate cancer and lymph node metastases of urothelial carcinomas of the renal pelvis." (PMID 28820475, 2017). "Our analysis of more than 2700 urothelial carcinomas revealed a frequent and mostly high-level expression of both TROP2 and EpCAM in non-invasive and invasive urothelial carcinomas." (PMID 38282671, 2023). "Of our 2,768 urothelial carcinomas, 2,580 (93.2%) were interpretable for both TROP2 and EpCAM." (PMID 38282671, 2023).
Ascites (4 papers, 2014 to 2021). Accumulation of fluid in the peritoneal cavity (between the layers of the peritoneum that lines the abdomen). "In a randomized clinical trial, there was a significant decrease in the need for drainage in patients suffering from EpCAM+ tumor associated ascites." (PMID 27650544, 2016). "The patients with ascites had more CK+vim- cells before treatment (p = 0.009) and less EpCAM-vim+ cells during treatment (p = 0.018) than the patients without ascites." (PMID 34440558, 2021). "EpCAM and CD44 are oncogenic glycoproteins commonly expressed by EOC solid tumours and ascites tumour cells." (PMID 26260289, 2015). "The expression of CD117, Oct4 and JAGGED was significantly up in paclitaxel-treated ascites tumor cells, while there was a trend in the increased expression of EpCAM, CD44 and NANOG but it was not significant compared to untreated control." (PMID 24886434, 2014).
B-cell lymphoma (4 papers, 2014 to 2024). "These are generated to bind CD16 on NK cells and one or two tumor antigens such as CD19 and CD20 (B-cell non-Hodgkin’s lymphoma), CD33 or CD33 and CD123 (AML), CD30 (Hodgkin’s lymphoma), EGFR or EpCAM (EGFR/EpCAM overexpressing carcinomas), and many others." (PMID 28405194, 2017).